HGF (hepatocyte growth factor)
Diseases named in the same sentence as HGF in open-access papers (continued):
Sharing a sentence is not in itself a finding about the gene and the disease.
melanoma (continued). "Our study demonstrates an exquisite sensitivity of the HGF+-driven melanoma model, to modest 50 % reductions in NM23-M1 and NM23-M2 expression, with all back skin tumors exhibiting lymph node and/or organ metastasis." (PMID 22699362, 2013). "In the HGF model, optimal induction of melanoma occurs when animals are treated with UV radiation 1–2 days after birth." (PMID 23470450, 2013). "Among animal models of melanoma, the HGF/SF transgenic mouse is of particular interest, as it possesses additional copies of HGF/SF gene that lead to extrafollicular localization of melanocytes." (PMID 24223113, 2013). "In contrast, black transgenic HGF/SF mice developed melanomas more rapidly and had more melanoma lesions per recipient than albino HGF/SF transgenics, and UVA induced melanoma only in the black animals." (PMID 24223113, 2013). "Expression of NM23-M1 and NM23-M2 in primary melanomas of the HGF+ × [m1m2]+/− group remained at the expected 50 % reduced levels relative to those obtained in HGF+ mice." (PMID 22699362, 2013). "There has been much development in the area of tumour-stroma interactions dictating treatment resistance, with much recent interest in how hepatocyte growth factor (HGF) can mediate BRAF-inhibitor resistance in melanoma." (PMID 23762429, 2013). "Our experimental design allows us to examine the potential role(s) of both selenoproteins and MeSeH at the initiation and progression stages of melanomagenisis in the HGF transgenic mouse model of UV-induced melanoma." (PMID 23470450, 2013). "The HGF+ strain is prone to UVR-induced melanoma with rapid growth characteristics but low metastatic potential." (PMID 22699362, 2013). "To determine the efficacy of Se as a melanoma prevention agent in vivo, we used a mouse model in which animals are engineered to express HGF in the skin." (PMID 23470450, 2013). "As expected, expression of NM23-M1 and NM23-M2 protein was reduced by approximately 50 % in cell lines established from HGF+ × [m1m2]+/− melanomas." (PMID 22699362, 2013). "Stable cell lines were established from the primary and metastatic melanoma lesions from these mice, with HGF+ × [m1m2]+/− lines exhibiting increased single cell migration and genomic instability." (PMID 22699362, 2013). "Recently, SLUG was reported to be regulated by HGF-dependent signaling pathways in human melanoma cells, and by TGF-beta and activin A in B16 murine melanoma cells." (PMID 22911700, 2012). "Transcriptome analysis of the various cell subsets purified from RETAAD tumors showed that PMN-MDSC express TGF-β1 and HGF, whereas melanoma cells express EGF." (PMID 21980263, 2011). "Consistent with such metastatic phenotype in vivo, derivative iMet melanoma cells showed robust invasion activity in response to HGF in Boyden chamber invasion assay in vitro." (PMID 20520718, 2010). "We proposed to identify novel molecules involved in melanoma development and progression analyzing the HGF specific signaling in the UV induced HGF transgenic melanoma mouse model." (PMID 19274086, 2009). "The UV-induced HGF mouse melanoma model recapitulates chronologically and histopathologically all the stages of human melanoma." (PMID 19274086, 2009). "Using the UV induced HGF transgenic mouse melanoma model to investigate the interplay among HGF signaling, RAS pathway and PI3K pathway in melanoma, we identified LKB1 as a protein directly modified by HGF induced signaling." (PMID 19274086, 2009). "In this matter, the phosphorylation state of LKB1Ser431 in spontaneous tumor samples raised in UV-irradiated HGF transgenic mice and in xenographed tumors from the 37-31E-melanoma cells correlated with elevated levels of p-Erk1/2." (PMID 19274086, 2009). "Our screening for the discovery of novel molecules involved in HGF signaling in melanoma cells allowed us to identify by DIGE analysis proteins that were directly modified in response to c-Met activation by HGF (data not shown)." (PMID 19274086, 2009).
melanoma (continued). "In summary, the activation of MET receptor in brain colonizing melanoma cells by stromal cell-released HGF may promote tumor self-maintenance and expansion and might counteract ICi therapy." (PMID 38386085, 2024). "Furthermore, fat cells secrete proangiogenic factors like hepatocyte growth factor (HGF) and VEGF, which contribute to the vascular mimicry associated with melanoma." (PMID 38921444, 2024). "Therefore, MET-expressing melanoma cells infiltrating the brain can benefit from the HGF-regulated systems that naturally occur in the brain and employ them as a survival strategy." (PMID 38386085, 2024). "Brain infiltrating melanoma cells hence may engage the HGF/MET signaling axis of brain cells and utilize it for regulation of survival and proliferation." (PMID 38386085, 2024). "Although we observed that MBM may provide HGF, whether and to which extent brain infiltrating melanoma cells provide HGF is unknown and needs additional investigation." (PMID 38386085, 2024). "However, following oncogenic transformation, melanoma cells gain expression of HGF, allowing autocrine c-MET/HGF signalling that functionally decouples melanoma cells from keratinocytes, facilitating invasion and migration." (PMID 37181747, 2023). "These siESRP1-transfected melanoma cells also demonstrated lower migratory potential under hepatocyte growth factor (HGF) treatment (HGF, a factor released during inflammation or tissue disruption, should increase the migration of CD44v6-positive melanoma cells)." (PMID 38106992, 2023). "Moreover, MET protein expression and MET phosphorylation after HGF stimulation were also documented in canine osteosarcoma and melanoma cell lines in that study, confirming activation of the receptor in vitro." (PMID 37104404, 2023). "While our data suggest that IL-6, HGF, and MCP-2 retain independent association with ORR, the nature of the relationship between these three inflammatory proteins in the context of advanced melanoma remains to be elucidated." (PMID 36007304, 2022). "Our findings are in line with an increasing body of evidence that the pro-inflammatory cytokine IL-6 can influence response to ICI in advanced melanoma, and further support a role of circulating HGF and MCP-2 levels as prognostic biomarkers as suggested by previous smaller studies." (PMID 36007304, 2022). "However, hypermethylated melanoma cell lines fail to upregulate CD73 following exposure to HGF/TNFα but do so only when pretreated prior to exposure with the demethylating agent 5-azacytidine." (PMID 33430239, 2021). "Herein, comparative gene expression profiling of normal tissue-derived fibroblasts and CAFs demonstrated the overexpression of a variety of growth and pro-angiogenic factors such as b-FGF, HGF, SCF, and VEGF, confirming the pro-mitogenic attitude of melanoma-associated fibroblasts." (PMID 34298873, 2021). "HGF/MET autocrine activation is a well-known process in the development of malignant melanoma." (PMID 34885093, 2021). "Interestingly, BRAF inhibitors induce reactive oxygen species (ROS) in melanoma cells, therefore, the aim of this study was to investigate a possible interplay between HGF/c-met and ROS sources, such as NADPH oxidases (Nox)." (PMID 33451139, 2021). "Similarly, HGF activation of the MET signaling pathway can decrease the response of BRAF-mutant melanomas to BRAF inhibition." (PMID 34071428, 2021). "In B16F10 mouse melanoma cells, cabozantinib inhibited invasion and migration mediated by HGF." (PMID 33918490, 2021). "Furthermore, FGF1 promotes tumor-niche fibroblasts to express and secrete HGF (hepatocyte growth factor), a mediator of angiogenesis and cell motility, and an important tumor-resistant factor in melanomas." (PMID 34830951, 2021). "Furthermore, it has been reported that CAF-derived HGF can promote melanoma progression by enhancing melanoma cell proliferation via tyrosyl-phosphorylation of MET, MAPK and ERK2." (PMID 34067929, 2021).
melanoma (continued). "Activated fibroblasts affect the acquisition of drug resistance in melanoma in various ways, a.o., through the secretion of growth factors, including HGF, insulin-like growth factor 1 (IGF1), and basic fibroblast growth factor (bFGF), which support cancer cell growth and proliferation." (PMID 33430277, 2021). "Stimulation of the HGF/c-met pathways could be the starting point that promotes several downstream processes that are crucial for melanoma development, such as proliferation, survival, motility, and invasiveness, including distant metastatic niche formation." (PMID 33451139, 2021). "Indeed, Prahallad and co-workers revealed that SHP-2 knockout clones of SK-Mel888 BRAF(V600E) mutant melanoma cells were unable to confer Vemurafenib resistance, following HGF, fibroblast growth factor 9 (FGF9), and stem cell factor (SCF) exposure." (PMID 33003469, 2020). "Indeed, the HGF-MET axis has been described as a mechanism of de novo resistance in a patient with a KIT-mutant melanoma." (PMID 32344828, 2020). "In addition, several lines of evidence point out a prominent role of the MET/HGF axis in tumor progression and resistance to therapy of several malignancies, including malignant melanoma." (PMID 32659961, 2020). "The use of air CAP using μ-DBD and the SN can minimize the malignancy effects of melanoma cells by describing HGF/c-MET molecular mechanism of acting on G-361 human melanoma cells and in mice xenografts, possibly leading to suitable targets for innovative anti-melanoma approaches in the future." (PMID 31126298, 2019). "Hepatocyte growth factor (HGF) secreted by fibroblasts leads to the resistance of BRAF-mutant melanoma to RAF inhibition via activation of the MAPK pathway, the PI3 K/AKT pathway, and the HGF receptor MET, while similar phenomena also appear in colorectal cancer." (PMID 30038550, 2018). "Thus, melanoma cell proliferation, survival, and acquisition of the metastatic phenotype can be supported by autocrine HGF/c-MET signaling." (PMID 30513872, 2018). "HGF might be a factor in the innate and acquired resistance of melanoma to oncoprotein-targeted drugs." (PMID 30513872, 2018). "Indeed, paracrine actions of HGF/SF in the HGF/SF model have been shown to impact lung colonization activity of melanoma cell allografts." (PMID 28788083, 2017). "MET activation, which may be driven by stromal HGF expression, has been shown to mediate melanoma growth, dissemination, and resistance to BRAF inhibition in multiple preclinical models." (PMID 28103611, 2017). "Here HGF rescued four of six NRAS mutant melanoma cell lines from MEK inhibition." (PMID 28147313, 2017). "Importantly, melanomas of hybrid crosses of the HGF/SF mouse with three different strains of mice harboring genetic alterations give rise to lymph node and organ metastasis." (PMID 28788083, 2017). "Furthermore, the c-Met receptor to which HGF binds exclusively is expressed and activated in melanoma cells and tumours, especially in those that harbour the NRAS mutation and non-mutated BRAF." (PMID 28708099, 2017). "In addition to providing a system for quantifying MRG activity, HGF/SF hybrids that exhibit robust metastatic melanoma are promising in vivo models for testing of novel therapeutics specifically directed to various aspects of the metastatic process." (PMID 28788083, 2017). "In addition, we showed that MAPK pathway inhibition induced rapid increases in MET and GAB1 levels, providing novel mechanistic insight into how BRAFV600E mutant melanoma is primed for HGF-mediated rescue." (PMID 28147313, 2017). "Taken together these data suggest that the increases in total MET and GAB1 may prime BRAF mutant melanoma cells for HGF-mediated rescue." (PMID 28147313, 2017).
melanoma (continued). "Another interesting aspect of our study is that it raised the question about the necessity of using bFGF, EGF and HGF in culture medium for in vitro investigation of melanoma biology and melanoma response to drugs targeting the RAF/MEK/ERK pathway in V600EBRAF melanoma cells." (PMID 28829835, 2017). "We show that melanoma cells orchestrate increased proliferation, invasion and migration using GH regulated intracellular signaling pathways and also upregulate oncogenic pathways like HGF-MET and ERBB3." (PMID 28223541, 2017). "However, we noted a significant reduction in the expression of hepatocyte growth factor (HGF) in lungs from multiple KO vs. WT melanoma-carrying animals." (PMID 28212574, 2017). "Three different growth factors, bFGF, EGF and hepatocyte growth factor (HGF) were used, either alone or in combination to reveal whether growth factors or their particular combination can influence the melanoma cell response to targeted therapy." (PMID 28829835, 2017). "The sensitivity of HGF/SF mice to UVR-induced melanoma has been attributed in large part to an HGF-induced shift of mouse skin melanocytes from their normal localization within the hair follicle to more external sites (i.e., UV-exposed) within the epidermis and at the dermal–epidermal junction." (PMID 28788083, 2017). "To this end, we crossed the HGF/SF and NME1/2+/− mouse strains in a C57BL/6 genetic background to measure the impact of NME1/NME2 deficiency on the metastatic potential of UV-induced melanoma." (PMID 28788083, 2017). "With studies in melanoma cell lines providing an increasing list of genes, genetic lesions, and gene expression profiles that exert metastasis-regulating activity, the HGF/SF model of UV-induced melanoma represents a valuable approach for measuring their respective activities in vivo." (PMID 28788083, 2017). "Previous in vitro study showed that suppression of the HGF/c-Met signaling pathway by quercetin, contributes to the anti-metastatic action and inhibit the cellular migration in melanoma cell lines and also inhibited the Wnt pathway in teratocarcinoma cell line." (PMID 27834805, 2016). "Moreover, recent studies in melanoma (HGF secreted by stromal cells inhibits cytotoxicity due to vemurafenib) have shown that tumour stroma is a major determinant of sensitivity of primary cancer cells to cytotoxic agents." (PMID 26573231, 2016). "In melanoma, HGF and c-Met are expressed and involved in tumorigenesis." (PMID 25971889, 2015). "HGF significantly enhanced the migratory abilities in melanoma A2058 and A375 cells." (PMID 25971889, 2015). "Quercetin dose-dependently suppressed HGF-stimulated melanoma cell migration and invasion." (PMID 25971889, 2015). "BRAF inhibitor resistance could be caused by HGF-triggered MET activation, and IGF-1 triggered its receptor activation in BRAF mutant melanoma." (PMID 24952482, 2014). "The identification ofstroma-mediated resistance in BRAF-mutant melanomas, through the secretion of hepatocytegrowth factor (HGF), therefore indicates a potential therapeutic strategy throughcombination treatment of RAF inhibitors and inhibition of the HGF activated pathway." (PMID 25490933, 2014). "Moreover, the finding of higher plasma levels of circulating HGF in BRAF mutant melanoma patients suggested a trend toward a worse prognosis for these patients." (PMID 28548075, 2014). "To assess the effects of antigenic reporters on response to molecularly-targeted therapeutic agents, we employed the melanoma GDA model HCmel12 (derived from an HGF/CDK4R24C-transgenic mouse), labeled ex vivo with ffLuc-eGFP, and transplanted subcutaneously into syngeneic GH or WT c-Brd mice." (PMID 25369133, 2014).
melanoma (continued). "Although poorly metastatic, HGF+ melanomas grow aggressively and often invade en masse into the subcutical layer of skin, suggesting metastasis is blocked at a later stage of the metastatic cascade (e.g. intravasation, survival in the circulation, extravasation or colonization/angiogenesis)." (PMID 22699362, 2013). "The current study demonstrates that nm23-m1 and nm23-m2 deficiency confers high metastatic potential to melanomas of the HGF+ strain, with aggressively-growing metastases occurring at sites analogous to those seen in human melanoma (i.e. lymph node, lung, liver and bone)." (PMID 22699362, 2013). "The lack of effect of NM23 deficiency on growth of HGF+-driven melanomas is consistent with prototypical metastasis suppressor activity, in which metastatic potential but not primary tumor growth per se is impacted." (PMID 22699362, 2013). "These two potential protective activities at both the initiation and progression stages were the basis of the design of our melanoma prevention study with the HGF mouse, where we examined the efficacy of SeMet when applied both before and after mutagenic insult (UV irradiation)." (PMID 23470450, 2013). "No macroscopic evidence of metastasis was associated with melanomas arising at any skin location for the HGF+ strain, consistent with the low metastatic potential described previously for this model system." (PMID 22699362, 2013). "In addition, cell lines generated from melanomas of the HGF+ × [m1m2]+/− hybrid exhibit increased motility and genomic instability, implicating functional roles for NM23 proteins in melanoma progression." (PMID 22699362, 2013). "We chose to investigate the potential interplay among the HGF RTK signaling, the RAS Ras-Erk1/2 and the PI3K-AKT pathways using the HGF transgenic mouse model in which HGF is over-expressed and which develops melanoma in response to neonatal ultraviolet (UV) radiation." (PMID 19274086, 2009). "Melanomas express basic fibroblast growth factor (bfgf), which they require for proliferation, and carcinomas that express high levels of the receptors egfr and Met secrete the corresponding factors tgfb or hepatocyte growth factor (hgf)." (PMID 22792017, 2006). "Therefore, metastatic melanoma cells expressing MET might scavenge HGF from the brain for activation of processes downstream of MET mediating survival and proliferation." (PMID 38386085, 2024). "In addition, epidermal growth factor (EGF) increases the levels of extracellular signal-regulated kinase 1/2 (ERK-1/2) with hair follicle-derived mesenchymal stem cell proliferation, and activation of p38 by hepatocyte growth factor (HGF) induces the proliferation of melanoma cells." (PMID 39338277, 2024). "Additionally, we identified CD8+c-Met+ tumor-infiltrating lymphocytes (TILs) in human melanoma skin biopsies, suggesting that targeting the HGF/c-Met pathway could control CD8+c-Met+ T cell-mediated anti-tumor immunity." (PMID 38137344, 2023). "However, hypoxia may confer resistance to vemurafenib by activating the hepatocyte growth factor/mesenchymal–epithelial transition factor (HGF/c-Met) pathway in melanoma cells." (PMID 36901857, 2023). "In melanoma, CD73 expression is influenced by sample type (e.g., primary, metastatic, or relapse tissue); therapy treatment; and presence of activating MAPK (e.g., BRAF) mutations, mitogenic and inflammatory signals [e.g., hepatocyte growth factor (HGF) and TNF-α], and necrosis." (PMID 32351498, 2020). "HGF was detected in melanoma-associated stromal cells in 68% BRAFV600E patient-derived biopsies from patients prior to treatment (23/34 biopsies), whereas, when 10 on-treatment biopsies were analyzed, HGF expression was found to be enhanced in 50% of them, compared to its pre-treatment level." (PMID 30513872, 2018).